SNORD29 (Small nucleolar RNA SNORD29 )
Gene: Small nucleolar RNA gene on chromosome 5 (24,811,481 to 24,811,548, forward strand). Ensembl gene ENSG00000223004.
Homologues: Orthologues: chimpanzee SNORD29 (96% identical), dog SNORD29 (75% identical), macaque SNORD29 (72% identical), guinea pig SNORD29 (69% identical), pig SNORD29 (69% identical), mouse Gm22744 (68% identical), pig SNORD29 (66% identical), rabbit SNORD29 (66% identical), rabbit SNORD29 (65% identical), rat LOC120100227 (65% identical), guinea pig SNORD29 (63% identical), tropical clawed frog SNORD29 (62% identical), and 1 more.
Diseases named in the same sentence as SNORD29 in open-access papers:
SNORD29 is named in the same sentence as 2 diseases in open-access papers, as found by Europe PMC text mining. Sharing a sentence is not in itself a finding about the gene and the disease. The quoted sentences say what the papers report.
infection (1 paper, 2022). The state of being infected such as from the introduction of a foreign agent such as serum, vaccine, antigenic substance or organism. "The silencing of SNORA/Ds encoded within RPS11 (SNORD35B), SNHG3 (SNORA73A, SNORA73B), and SNHG1 (SNORD22, SNORD25, SNORD26, SNORD27, SNORD28, SNORD29, SNORD30, SNORD31) inhibited infection with influenza A virus." (PMID 36430145, 2022).
SNORD29 also shares sentences with these, for which no sentence is quoted: viral infections (1 paper).